GSK3B (glycogen synthase kinase 3 beta)
Diseases named in the same sentence as GSK3B in open-access papers (continued):
Sharing a sentence is not in itself a finding about the gene and the disease.
colorectal cancer (continued). "Prior studies have shown that in colorectal cancer and esophageal squamous cell carcinoma, YTHDF2 activates this pathway by targeting m6A-modified GSK3β and APC mRNAs for degradation." (PMID 38637831, 2024). "ECM1 was oncogenic, which promoted colorectal cancer proliferation and progression via PI3K/AKT/GSK3B/Snail pathway signal." (PMID 38062443, 2023). "This study also demonstrated that hub genes (IL1B, GSK3B, NOS3, RELA, and CDK4) were most likely to be involved in the effects of oxidative stress brought on by geniposide in the prevention of colorectal cancer." (PMID 37894904, 2023). "Our PPI network analysis results showed that IL1B, GSK3B, NOS3, RELA and CDK4 were related to oxidative stress induced by geniposide against colorectal cancer." (PMID 37894904, 2023). "The evolving evidence suggested that GSK3β phosphorylated KLF5, thereby promoting Fbw7‐mediated KLF5 ubiquitination in colorectal cancer." (PMID 37461162, 2023). "In colorectal cancer, ZEB2 undergoing glycogen synthase kinase-3 beta (GSK3β) phosphorylation shows migratory potential, while ectopic expression of ubiquitin-specific protease 14 (USP14) is linked to liver and lymph node metastasis." (PMID 37174083, 2023). "Around half of the CRLM1 peak genes were related to either increased or decreased gene expression, including increased expression of colorectal cancer genes SMAD2, MAPK9, and GSK3β, as well as three members of GALNT family." (PMID 35907898, 2022). "Further studies evaluating the clinical significance of the PGC-1α/LARS1/AKT/GSK-3β/β-catenin axis in human colorectal cancer patients and therapeutic potentials of several LARS1 inhibitors in PGC-1α-overexpressing colorectal cancer are needed." (PMID 36612155, 2022). "GSK3β phosphorylates ZEB2 at Ser705 and Tyr802 in colorectal cancer; this induces EMT, colorectal cancer-cancer stem-like cell properties and metastasis." (PMID 36499447, 2022). "In colorectal cancer, WNT/β-catenin and RAS/ERK signalling pathways interacted with active GSK3β as a mediator." (PMID 35216190, 2022). "ANXA2 was reported to activate AKT/GSK3β and AKT/mTOR signaling in gastric, breast, and colorectal cancer, whereas ANXA2 is a substrate of ITSN1-L-mediated cell–substrate adhesion through the FAK/integrin β3 pathway." (PMID 35977942, 2022). "As a model for GSK3β knockout, we selected Talen-induced knockout cells (HCT116-GSK3β-KO) and a paired isogenic control cell line (HCT116-GSK3β-WT) in the colorectal cancer cell-line HCT116." (PMID 34739494, 2021). "Our findings also pose the possibility that PRMT5 promotes colorectal cancer cell growth, cell cycle progression, and EMT via EGFR/Akt/GSK3β signaling axis." (PMID 33495409, 2021). "PI3Kδ was reported to promote breast and prostate cancer cell proliferation via dampening of PTEN activity and to induce colorectal cancer cell growth and invasion by activating the AKT/GSK3β/β-catenin signaling pathway." (PMID 34108491, 2021). "GSK3β, a member of the GSK3 family of serine/threonine protein kinases, is aberrantly activated in various cancer types, including colorectal cancer." (PMID 34868956, 2021). "While CSN2 has been shown to regulate SNAIL stability through inhibiting its phosphorylation by GSK-3β, CSN6 has been shown to be overexpressed in colorectal cancer and involved in its development." (PMID 29755680, 2018). "In non-small cell lung cancer and colorectal cancer, PGE2 enhances β-catenin nuclear localization and inhibits GSK3β by phosphorylation which is dependent on cAMP and kinase activity of PKA." (PMID 25266063, 2015). "Among the three members APC, Axin1, GSK3β and CKIα of the destruction complex family, only Axin1 co-precipitated with 5-HT1DR in 5-HT1DR overexpression LoVo colorectal cancer cells." (PMID 26214021, 2015).
colorectal cancer (continued). "This polyphenol from green tea inhibits colorectal cancer stem cells through the down-regulation of the Wnt/β-catenin signaling pathway, the up-regulation of GSK-3β (glycogen synthase kinase 3 beta), which is the key negative regulator of the Wnt signaling pathway." (PMID 39859345, 2025). "Additionally, the POP112 line did not harbour mutations or deep amplifications or deletions in the WNT pathway members defined as colorectal cancer drivers APC, AXIN1, AXIN2, CTNNB1, GSK3B or RNF43, and only a shallow deletion in ZNRF3." (PMID 38324534, 2024). "Additionally, our in vivo results verified that MIF regulates the biological behaviour of colorectal cancer cells by targeting SLC3A2 and regulating the AKT/GSK‐3β signalling pathway." (PMID 35567291, 2022). "To confirm whether PGC-1α regulates the expression levels of LARS1, p-AKT, p-GSK-3β, p-mTOR, p-S6K1, p-4EBP1, β-catenin, c-Myc, cyclin D1, and vimentin in other colorectal cancer HT-29 and SNU-C4 cells, we performed qRT-PCR and Western blot analysis." (PMID 36612155, 2022). "Additionally, we also analyzed β-catenin and GSK-3β in HCT-116 cells, which mediate increased proliferation, migration, and invasion via activation of the Wnt/β-catenin pathway in colorectal carcinoma." (PMID 36012587, 2022). "Our study also proves that PRMT5 promotes cell proliferation and EMT in human colorectal cancer via activation of the EGFR/Akt/GSK3β signaling axis, but not ERK1/2 or PTEN/mTOR signaling pathways, which is strongly linked to the PRMT5 enzyme activity." (PMID 33495409, 2021). "We used an isogenic pair of colorectal cancer cell lines (HCT116-GSK3β-WT and HCT116-GSK3β-KO) and showed that canonical Wnt signalling is largely unimpaired by complete knockout of GSK3β whereas specific and dramatic effects on cell-cell adhesion proteins and metabolic pathways were observed." (PMID 34739494, 2021). "In colorectal cancer cells, ERK/GSK-3β/snail signaling pathway is also activated by CXCL522." (PMID 32632106, 2020). "If SHIP1 has a functional role in colorectal cancer, it could be involved in PI3K/AKT/GSK3β/β-catenin signaling." (PMID 32679836, 2020). "Western blot analysis revealed that phosphorylation of GSK3β at serine 9 was not reduced but rather increased upon SFN treatment in colorectal cancer cells." (PMID 30338040, 2018). "Moreover, 10−5 M BPA regulated the stability of Snail by the protein kinase B/glycogen synthase kinase-3β (Akt/GSK-3β) signaling pathway and significantly upregulated the expression of Twist, inducing the occurrence of EMT in colorectal cancer cells." (PMID 29323181, 2018). "For example, inhibition of GSK3β has prevented cell proliferation in colorectal cancer cells, whereas a decrease in GSK3β expression has been observed in non-melanoma skin cancer cells." (PMID 28924210, 2017). "Also, restoring the expression of GSK3β and SFRP2 restrained miR-224-induced aggressive phenotype of colorectal cancer cells." (PMID 26822534, 2016). "The immunoreactivity of GSK3β, axin 1 and ubiquitin proteins was significantly higher (p=0.03, p=0.039 and p=0.03, respectively) in colorectal carcinoma than in the colonic adenoma and adjacent non-neoplastic mucosa." (PMID 27462886, 2016). "We found that draxin-induced growth cone collapse critically depends on draxin receptors (deleted in colorectal cancer, DCC), inhibition of protein kinase B/Akt, activation of GSK-3β (glycogen synthase kinase-3β) and the presence of microtubule-associated protein MAP1B." (PMID 25775433, 2015). "Similarly, GSK3β depletion in HT29 colorectal cancer cells led to a reduction in both SRSF1 and SRPK1 protein levels, suggesting an indirect effect of GSK3β on SRSF1 via SRPK1." (PMID 26273603, 2015). "Similarly, the up-regulation of COX-2 in colorectal cancer leads to production of PGE2 which binds to the EP3 receptor leading to PI3K and PKB activation, phosphorylation and dissociation of GSK3β and thereby inhibition of the destruction complex." (PMID 22168384, 2011).
colorectal cancer (continued). "Altogether, these results implicate that PGC-1α regulates cell proliferation and invasion through modulation of the LARS1/AKT/GSK3β/β-catenin axis and that LARS1 might be a potential therapeutic target for PGC-1α-overexpressing human colorectal cancer as depicted in a schematic diagram." (PMID 36612155, 2022). "The Western blotting assays showed that glycyrol significantly reduced the expression of E-cadherin, β-catenin, c-Myc, and GSK-3β proteins in RKO cells, suggesting that glycyrol may inhibit the growth of colorectal cancer RKO cells via the Wnt/β-catenin signaling pathway." (PMID 36295798, 2022). "Moreover, GSK3β reduces MZF1 expression, leading to c-MYC downregulation in colorectal carcinoma." (PMID 36499054, 2022). "For example, in colorectal cancer, luteolin was reported to inhibit the translocation of β-catenin from the cytosol to the nucleus by modulating the expression of GSK-3β31, while, our results demonstrated that luteolin-induced inhibition of Wnt signaling in PCa cells is GSK-3β independent." (PMID 29867083, 2018). "Additionally, overexpression of CXCL5 enhanced the migration and invasion of colorectal cancer cells by inducing the epithelial-mesenchymal transition (EMT) through activation of the ERK/Elk-1/Snail pathway and the AKT/GSK3β/β-catenin pathway in a CXCR2-dependent manner." (PMID 28356111, 2017). "Finally, expression analyses of miR-224, GSK3β and SFRP2 in 20 clinical colorectal cancer tissues revealed significant negative correlations between miR-224 and the expression of GSK3β and SFRP2." (PMID 26822534, 2016).
lung carcinoma (159 papers, 2003 to 2025). "Annexin-V staining and PARP Western blots also revealed that the GSK3β inhibitor CHIR99021 significantly increased apoptosis in FHIT-deficient lung cancer cells." (PMID 39762409, 2025). "We noted that FHIT loss activated both the HRR and NHEJ repair pathways in lung cancer cells and that the GSK3β inhibitor inhibited both pathways." (PMID 39762409, 2025). "We showed that a GSK3β inhibitor selectively inhibited FHIT-deficient lung cancer by inhibiting the ATR/BRCA1/RAD51 signaling axis and BRCA1/RAD51 transcription, leading to the inhibition of HRR and genotoxic cell death." (PMID 39762409, 2025). "FHIT-deficient lung cancer cells were more sensitive to the GSK3β inhibitor than FHIT-proficient cells were in all three FHIT-isogenic pairs tested." (PMID 39762409, 2025). "In this study, we found that GSK3β inhibition is synthetic lethal with FHIT loss in lung cancer cells." (PMID 39762409, 2025). "Pharmacological inhibition or siRNA depletion of GSK3β selectively suppressed the growth of FHIT-deficient lung cancer tumors in vitro and in animal models." (PMID 39762409, 2025). "Cyclometalated Ru(II)-isoquinoline complexes caused apoptosis in cisplatin-resistant lung cancer A549/DDP cells by modulating Akt/GSK-3β/Fyn signaling." (PMID 38104089, 2023). "In A549 lung cancer cells, nobiletin decreased the expression of Akt, GSK3β, β-catenin, and multidrug resistance-associated protein (MRP1) expression, while it increased caspase-3-mediated apoptosis and polymerase cleavage." (PMID 37568796, 2023). "Tivantinib showed higher potency for GSK-3α more than for GSK-3β and the inhibition of GSK-3α or GSK-3β expression caused apoptosis in lung cancer cells." (PMID 27049759, 2016). "In lung cancer, it was shown that GSK3β also phosphorylates Slug protein, causing its ubiquitination by the E3 ligase, carboxyl terminus of Hsc70-interacting protein (CHIP), for proteasomal degradation." (PMID 24550888, 2014). "The study suggests that targeting GSK3β could lead to new treatments for lung cancer with FHIT loss, offering hope for better therapies." (PMID 39762409, 2025). "Hirsutine causes lung cancer cell death by GSK3β-mediated mPTP opening." (PMID 35370635, 2022). "Interestingly, IL-17RB signaling through the ERK/GSK-3β/β-catenin pathway has been associated also with EMT in lung cancer." (PMID 32373132, 2020). "In this study, our in vitro results show, for the first time, a participation of the widespread β1-integrin subunit-associated protein kinases, ILK, PKBα/Akt, GSK-3β within the radiation response of a human lung cancer cell line as well as normal human lung primary fibroblasts." (PMID 12778079, 2003). "Similarly, a study using the lung cancer cell lines A549 and ASCT-a-1 revealed that resveratrol treatment led to a significant decrease in AKT phosphorylation, which in turn caused a suppression in GSK-3β phosphorylation and an increase in lung cancer cell death." (PMID 41217667, 2025). "DHA decreased the ability of the AKT/GSK3-β/cyclin D1 signaling pathway to proliferate in the A549 lung cancer cell line." (PMID 41217667, 2025). "Schwann cells, through secreting C-X-C motif chemokine ligand 5 (CXCL5), activate the PI3K/AKT/GSK-3β/Snail-Twist signaling pathway in lung cancer cells, mediates EMT, and increases the motility, invasiveness, and metastatic potential of lung cancer cells." (PMID 39981185, 2025). "In this study, we employed a synthetic lethal drug screening approach to target lung cancer with FHIT loss and identified GSK3β as a synthetic lethal partner of FHIT in lung cancer cells." (PMID 39762409, 2025). "This study highlights that GSK3β, as well as the HRR pathway, is a potential actionable target in FHIT-deficient lung cancer and provides the first candidate for FHIT-targeting synthetic lethal therapy for smokers with lung cancer." (PMID 39762409, 2025).
lung carcinoma (continued). "This study revealed that the GSK3β and HRR pathways are new targets for developing FHIT loss-associated targeted therapies for lung cancer in smokers." (PMID 39762409, 2025). "In another study on lung cancer cells, it was found that knock down of PKCα inhibits the downregulation of PD-L1 induced by GSK3β dephosphorylation." (PMID 39809736, 2025). "Our study provides strong evidence that inhibiting the GSK3β and HRR pathways is a promising strategy for targeting FHIT loss in smokers with lung cancer." (PMID 39762409, 2025). "We further investigated the effects of the GSK3β inhibitor on the HRR and NHEJ signaling pathways in FHIT-wild-type and FHIT-deficient lung cancer cells." (PMID 39762409, 2025). "Here, we report that inhibitors of glycogen synthase kinase 3 beta (GSK3β) and the homologous recombination DNA repair (HRR) pathway are synthetic lethal with FHIT loss in lung cancer." (PMID 39762409, 2025). "The findings of this study suggest that the GSK3β and HRR pathways are potential drug targets in lung cancer patients with FHIT loss." (PMID 39762409, 2025). "Cordycepin inhibits the ERK/Slug signalling pathway through the activation of GSK3β which, in turn, upregulates Bax, and leading to apoptosis of the lung cancer cells." (PMID 41397932, 2025). "NOB can overcome Adriamycin resistance in lung cancer cells, and enhance the chemotherapy to Adriamycin through the Akt/GSK3β/β-catenin/MYCN/MRP1 pathway." (PMID 41425709, 2025). "They tested drugs on lung cancer cells and discovered that blocking GSK3β (an enzyme involved in various cell processes) killed FHIT-deficient cells." (PMID 39762409, 2025). "To evaluate the in vivo therapeutic effect of the GSK3β inhibitor on lung cancer with FHIT loss, we performed tumor xenograft experiments with parental and FHIT−/− HCC827 lung cancer cells in athymic nude mice." (PMID 39762409, 2025). "In a lung cancer model, MiR-1246 target mRNA for GSK-3β and β-catenin, thus regulating the Wnt-pathway." (PMID 38899393, 2024). "Recent studies indicated that both strands of miR-4732-5p and miR-4732-3p prevented lung cancer aggressiveness through inhibited TBX15/TNFSF11 axis or PI3K/Akt/GSK3β/Snail pathway." (PMID 39337462, 2024). "In line with this, sulforaphane has been found to decrease the expression of miR-616-5p, thus restraining epithelial-mesenchymal transition (EMT), and the metastasis of lung cancer through the miR-616-5p/GSK3β/β-catenin signaling pathway." (PMID 38972997, 2024). "A recent report uncovered that HOXA4 affected lung cancer progression by inhibiting the Wnt-b-catenin signaling through GSK3B up-regulation." (PMID 37898994, 2024). "Cyclometalated Ru(II)-isoquinoline complexes alter Akt/GSK-3β/Fyn signaling in cisplatin-resistant lung cancer A549/DDP cells." (PMID 38830859, 2024). "Taken together, the data indicate that a CD38/A2AR axis regulates Snail‐dependent lung cancer cell EMT through the AKT/GSK‐3β pathway." (PMID 38545257, 2024). "Sulforaphane has been shown to decrease the levels of miR-616-5p and GSK3β/β-catenin signaling and to increase S/G2–M phase cell cycle arrest in lung cancer cell lines H1299, 95-C, and 95-D." (PMID 37568796, 2023). "Here, we found that Gsk3b, Notch2, Pik3cb, Myc, Cdkn1a, and Smad3 were increased in human lung cancer tissue and Cd‐transformed cells, while Pik3cb, Myc, Cdkn1a, and Smad3 were negatively correlated with circCIMT." (PMID 36814305, 2023). "Functional activities of Rac1 correlating with the enhanced activation of Akt and GSK3β play an important role in lung cancer metastasis." (PMID 37612265, 2023). "Mechanistically, the dimethylation of KLF5 by PRMT5 promotes the maintenance and proliferation of lung cancer cells at least partially by stabilising KLF5 via regulation of the Akt/GSK3β signalling axis." (PMID 37461162, 2023). "GK inhibits the Akt/GSK-3β/Snail pathway and Wnt/β-catenin pathway to prevent lung cancer invasion and spread." (PMID 36937843, 2023).